IL13 (interleukin 13)
Diseases named in the same sentence as IL13 in open-access papers (continued):
Sharing a sentence is not in itself a finding about the gene and the disease.
pulmonary fibrosis (continued). "IL-13 has been shown to contribute to inflammation and fibrosis in multiple animal models of pulmonary fibrosis including bleomycin-induced pulmonary fibrosis." (PMID 33171668, 2020). "Previous studies have indicated that multiple cytokines, including TGF-β1, IL-1β, TNF-α, IL-17, IL-27, IL-13, and IL-32, are overexpressed in pulmonary fibrosis." (PMID 33097029, 2020). "IL-13 is the predominant regulator of fibrotic tissue remodeling in several models of fibrosis such as idiopathic pulmonary fibrosis (IPF) and radiation-induced fibrosis." (PMID 31398940, 2019). "IL-13Rα2 displays greater affinity for IL-13, suppressing IL-13-IL-13Rα1-induced responses and, consequently, pulmonary fibrosis." (PMID 31398940, 2019). "On the same line, a murine model showed that IL-33, an alarmin of the IL-1 family related to inflammation and fibrosis, favours IL-13-dependent lung fibrosis." (PMID 30809542, 2019). "IL-13 was known to be expressed by not only Th2 cells but also human M2 macrophages among patients with pulmonary fibrosis as well as in mouse alveolar macrophages exposed to instilled particles." (PMID 30520685, 2019). "A molecular network linking macrophage activation, eosinophil recruitment and pulmonary fibrosis was generated using the transcriptional profiles, highlighting a central role of IL-13 and IL-4 in pathogenesis and cell recruitment/activation." (PMID 31469835, 2019). "On the other side, expression of IGF-1 is inhibited by Th1 cytokine IFN-γ and induced by Th2 cytokines IL-4 and IL-13, while pulmonary fibrosis is a typical Th2 response that IL-4 and IL-13 predominate." (PMID 30018981, 2018). "Among the cytokines and chemokines that were upregulated by bleomycin administration and suppressed by S1pr2 deletion, IL-13 has recently emerged as a profibrotic mediator in lung fibrosis." (PMID 29782549, 2018). "We found that genetic deletion of S1pr2 dramatically inhibited bleomycin–induced lung fibrosis through the mechanisms involving the potentiation of the responses to the profibrotic cytokine IL-13." (PMID 29782549, 2018). "The overexpression of IL-13 in the airway also shows the excessive secretion of mucus and inflammation and eventually leads to pulmonary fibrosis." (PMID 29541141, 2018). "Enhanced production of TGF-β and IL-13 are essential for the development of pulmonary fibrosis by inducing myofibroblast differentiation and stimulating the production of extracellular matrix components, such as collagen." (PMID 30405626, 2018). "Administration of anti-IL-13 antibody into wild-type mice substantially inhibited bleomycin–induced lung fibrosis compared with control IgG." (PMID 29782549, 2018). "We tested a possible involvement of IL-13 in a repeated bleomycin injection model of lung fibrosis by studying the effect of anti-IL-13 antibody administration in mice." (PMID 29782549, 2018). "A previous study has shown that reduction of IL-4- and IL-13-responsive macrophages and mononuclear cells using IL-13-Pseudomonas exotoxin A fusion protein attenuates bleomycin-induced lung fibrosis in mouse models." (PMID 29038604, 2017). "TGF-β and IL-13 are essential for the development of pulmonary fibrosis by promoting differentiation of myofibroblast and stimulating production of extracellular matrix, such as collagens." (PMID 28202030, 2017). "In this model IL-33 activates M2 macrophages to produce IL-13 and TGF-β1, and then further induces the expansion of ILC2s to produce IL-13, ultimately resulting in the development of pulmonary fibrosis." (PMID 28271447, 2017). "Group 3 ILCs promoted bleomycin-induced pulmonary fibrosis by secreting IL-17, whereas IL-25 induced expansion of the group 2 ILCs within the lungs, which promoted pulmonary fibrosis via IL-13 dependent mechanism." (PMID 27597803, 2016).
pulmonary fibrosis (continued). "Although IL-13 contributes to pulmonary fibrosis, lung tissue levels of pro-allergic cytokines such as IL-4 and IL-13 were very low in all groups (<0.5 pg/mg), and IL-5 did not have consistent time- or concentration-dependent responses (data not shown)." (PMID 27083413, 2016). "It has been reported that IL-13 induces lung fibrosis, and IL-13 antagonist have been tested in lung fibrosis and other lung diseases." (PMID 25775215, 2015). "Our selection includes cytokines previously associated with the lung response to radiation in both mice and humans such as Il6 and Tnfα) as well as pulmonary fibrosis-promoting Il1β, Il13 and Il17) and anti-fibrotic mediators Il10 and Ifnγ." (PMID 25889053, 2015). "STAT6 also lies downstream of IL-4 and IL-13, which exhibit increased levels in human airway inflammatory diseases and are believed to play key roles in progression of pulmonary fibrosis." (PMID 25944985, 2015). "Thomas A Wynn (National Institute of Allergy and Infectious Disease, NIH, Bethesda, MD, USA) gave a talk on the roles of Tgf-β1, Il-13, and inflammatory mediators in mouse models of pulmonary fibrosis." (PMID 24484528, 2014). "He mentioned that pulmonary fibrosis induced by chronic allergen exposure is Il-13 dependent, while bleomycin-induced fibrosis is mediated by Il-17A produced by CD4+ T cells and γδ+T cells." (PMID 24484528, 2014). "Levels of IL-13 are higher in patients with pulmonary fibrosis as compared to controls, and macrophages isolated from these fibrotic lungs produce more IL-13 than macrophages from control lungs." (PMID 23533311, 2013). "Multiple studies have demonstrated that IL-13 is essential for the development of dermal, gastrointestinal, and pulmonary fibrosis, as well as fibro-obliterative lesions found in the bronchiolitis obliterans (BO) syndrome." (PMID 24143891, 2013). "Anti-IL-13 monoclonal antibody QAX576 (NCT00532233, by Novartis, Basel Switzerland) completed phase II clinical trials recruiting patients with idiopathic pulmonary fibrosis to treatment with single dose QAX576 to measure IL-13 production." (PMID 23283176, 2011). "The infection with live pathogen addressed, in part, our concern regarding its impact on the therapeutic effectiveness of IL13-PE in pulmonary fibrosis." (PMID 20090941, 2010). "Do circulating IL13-PE-specific antibodies neutralize the therapeutic effects of intranasally delivered IL13-PE during pulmonary fibrosis?" (PMID 20090941, 2010). "Given that the systemic sensitization to IL13-PE resulted in appearance of neutralizing antibodies in the serum, we next evaluated the influence of these antibodies on the therapeutic effect of IL13-PE against pulmonary fibrosis." (PMID 20090941, 2010). "Together, these findings further bolster the prospects of IL13-PE as a clinically useful therapeutic in the treatment of pulmonary fibrosis." (PMID 20090941, 2010). "Overall, we found that despite the strong immunogencity of an active infection with P. aeruginosa or systemic sensitization with IL13-PE, the intranasal delivery of IL13-PE robustly inhibited bleomycin-induced pulmonary fibrosis." (PMID 20090941, 2010). "As we have observed previously, mice that received bleomycin developed severe pulmonary fibrosis but the introduction of four intranasal doses of IL13-PE (1000 ng/dose between days 21 and 28 after bleomycin ameliorated this fibrotic response." (PMID 20090941, 2010). "Studies using a bleomycin-induced pulmonary fibrosis demonstrated that IL-13 signaling through the IL-13α2 receptor is involved in induction of TGF-β1 production and fibrosis." (PMID 20738867, 2010). "Specifically, lungs from mice that received saline showed a marked reduction in lung fibrosis after intranasal treatment with either 200 or 1000 ng/dose of IL13-PE (left side of Figure)." (PMID 20090941, 2010).
pulmonary fibrosis (continued). "Surprisingly, both of these events provide protective effects either by reducing the fibrotic response (as in the case of infection) or sparing mice from the lethal effects of pulmonary fibrosis (as in the case of systemic IL13-PE sensitization)." (PMID 20090941, 2010). "IL-13 is elevated after administration of bleomycin in murine lungs and enhanced IL-13Rα2 signaling is thought to be involved in bleomycin-induced lung fibrosis." (PMID 21067601, 2010). "Surprisingly, histological analysis showed that a prior P. aeruginosa infection attenuated the development of bleomycin-induced pulmonary fibrosis, which was modestly further attenuated by the intranasal administration of IL13-PE." (PMID 20090941, 2010). "Mice over-expressing the Th2 cytokines IL-4 or IL-13 in their lungs exhibit features of COPD and pulmonary fibrosis in association with adenosine elevations." (PMID 20169073, 2010). "Based on these observations, they suggested that IL-4/IL-13-induced Retnla was playing a direct role in myofibroblast differentiation and in the pathogenesis of pulmonary fibrosis." (PMID 19381262, 2009). "IL-13 expression is not only in T cells and mast cells but also in both normal alveolar macrophages and those from subjects with pulmonary fibrosis." (PMID 16083514, 2005). "respiratory disease dataset, we observed significant enrichment of IFNγ signatures in cystic fibrosis and COVID‐19 infection, IL‐33 in COPD and COVID‐19, IL‐4 + IL‐13 in pneumonia, and TGFβ signatures in pulmonary fibrosis (PF) and chronic rhinosinusitis (CRS)." (PMID 40926620, 2025). "Studies have indicated that eucalyptol can alleviate bleomycin-induced pulmonary fibrosis, suppressing the expression of arginase-1, Ym-1, IL-13, and transforming growth factor (TGF)-β1, as well as reducing the production of IL-13, IL-6, and TNF-α, which inhibits M2 macrophage polarization." (PMID 39910395, 2025). "CCL-2 attracts fibrocytes to distinct injuries, and interestingly, the interplay among TGF-β, CCL-2, and IL-13 has been observed in pulmonary fibrosis, suggesting that it may also play a role in tumor fibrosis." (PMID 40362499, 2025). "Indeed, previous studies have shown that IL13 plays an important role in the development of lung fibrosis." (PMID 38642135, 2024). "In BALF, the concentrations of platelet-derived growth factor (PDGF), connective tissue growth factor (CTGF), and the profibrotic T helper 2 cytokine IL-13 were significantly elevated in both WT and TG mice with lung fibrosis compared to their respective saline-treated controls." (PMID 39329706, 2024). "In addition to IL-4 and IL-13, it has been observed that IL-5 can also play a role in tissue remodeling in several diseases including pulmonary fibrosis." (PMID 37063828, 2023). "Recently, using a statistical approach, it has been shown that IL-13 in combination with matrix stiffness is able to regulate macrophage morphology, M2 polarization profile, and reduced phagocytosis, as well as efferocytosis at least in pulmonary fibrosis." (PMID 37629063, 2023). "Conversely, miR-142-5p overexpression seem to contribute to the establishment of chronic inflammatory diseases, sustaining profibrogenic properties of macrophages induced by IL-4 and IL-13 and showing upregulation in macrophages from tissue samples of patients with idiopathic pulmonary fibrosis." (PMID 36972298, 2023). "Given the fact that Th2 cytokines serve as essential regulators for generating and maintaining a fibrotic microenvironment in the late stage of pulmonary fibrosis, we stimulated macrophages with cytokines IL-4 and IL-13 together, to stimulate the Th2 microenvironment." (PMID 37523510, 2023). "Similarly, in a pulmonary fibrosis model, IL-13 antagonization reduced fibrosis and collagen deposition." (PMID 37629063, 2023). "Moreover, lung biopsies from patients suffering from idiopathic pulmonary fibrosis also exhibited elevated levels of IL-13 and IL-4." (PMID 36982747, 2023).
pulmonary fibrosis (continued). "DKK1 enhanced IL-13-mediated gene expression profiles in pulmonary fibrosis." (PMID 38162655, 2023). "In the middle and late stages of the disease, IL-33 induces ILC2 hyperactivation, differentiation of alternately activated M2 macrophages, and the secretion of TGF-β and IL-13 from mast cells, resulting in the transformation of epithelial cells to mesenchymal cells and leading to pulmonary fibrosis." (PMID 36362440, 2022). "Therefore, dexamethasone or anti-IL-13 can delay the progress of pulmonary fibrosis by preventing the progress of EMT." (PMID 35592688, 2022). "IL-33 can also induce pulmonary fibrosis by promoting ST2/IL-13/IL-4Rα-mediated AAM activation." (PMID 36362440, 2022). "IL-13 and IL-17 are endowed with potent profibrotic capacity with relevance to lung fibrosis." (PMID 35954255, 2022). "IL‐25 promotes lung fibrosis in a IL‐13+IL‐17BR+ILC2 dependent fashion." (PMID 36082495, 2022). "Periostin, induced by the Th2 cytokines IL-4 and IL-13, has been reported to be involved in pulmonary fibrosis with crosstalk of transforming growth factor-β21,22, and serum periostin could be a good predictor of decreased lung function and poor prognosis." (PMID 36380088, 2022). "IL-13 has been shown to play a key role in lung fibrosis from several stimuli, including radiation." (PMID 36173617, 2022). "Tralokinumab blockade of IL-13 attenuated lung fibrosis in a humanized mouse model of IPF." (PMID 34305927, 2021). "Anti-IL-13 (tralokinumab) can improve lung fibrosis in asthmatic patients." (PMID 34070405, 2021). "IL-13, a crucial regulator of the fibrotic extracellular matrix, is produced by activated Th2 cells and has been proven to play a role in many inflammatory and fibrotic diseases, such as idiopathic pulmonary fibrosis and systemic sclerosis." (PMID 32855969, 2020). "Surprisingly, a recent study suggests that IL-13 could be a therapeutic target for radiation-induced pulmonary fibrosis." (PMID 32117962, 2020). "In a murine model of pulmonary fibrosis, IL-13 has been shown to induce fibroblast migration via IL-13-mediated enhanced formation of lamellipodia, cytoskeletal projections at the leading edge of the cells, as well as enhanced matrix metalloproteinases (MMPs) activity." (PMID 30101408, 2019). "Daily intraperitoneal administration of JSI-124 (1 mg/kg) from day 14 to 28 reduced JAK2 and STAT3 phosphorylation as well as the increased protein levels and cell numbers in BAL, lung mass and protein, and expression of IL-6 and IL-13 secondary to lung fibrosis." (PMID 29409529, 2018). "Future studies are warranted to determine if a subset of pulmonary fibrosis patients with elevated type 2 cytokines such as IL-13 may increase eotaxin production coupled with worse fibrosis and clinical outcomes." (PMID 29672593, 2018). "Our data indicate that IL-13 is a key driver for the repeated injection model of lung fibrosis." (PMID 29782549, 2018). "Finally, we determined that therapeutic neutralization of IL-13, during the period of IL-13Rα2 saturation was sufficient to protect mice from lung fibrosis." (PMID 28004808, 2016). "Using a mouse model, we tested the hypothesis that IL-13 drives the progression of radiation-induced pulmonary fibrosis." (PMID 28004808, 2016). "In addition, profibrotic cytokines, such as TGF-β and IL-13, contribute to pulmonary fibrosis by promoting the conversion of fibroblasts to myofibroblasts." (PMID 27144583, 2016). "Irradiated IL-13 deficient mice did not develop extensive pulmonary fibrosis, and displayed no significant change in hydroxyproline content or YM-1 concentration at 16 weeks after irradiation relative to unirradiated controls." (PMID 28004808, 2016). "The role of macrophages in lung fibrosis was confirmed as Ccr2−/− mice showed markedly reduced lung fibrosis compared with wild-type mice upon challenged by bleomycin, while transferring of monocytes or M(IL-13) recapitulated lung fibrosis in the Ccr2−/− mice." (PMID 26436920, 2015).
pulmonary fibrosis (continued). "Among them, IL-13 is thought to be important cytokine in the pathogenesis of asthma, and more recently has been shown to play a pivotal role in a number of fibrotic diseases including hepatic and pulmonary fibrosis, and nodular sclerosing Hodgkin’s disease." (PMID 25775215, 2015). "Moreover, transferring M(IL-13), particularly from 12 to 24 days following bleomycin challenge, generated much stronger lung fibrosis compared with transferring unactivated monocytes." (PMID 26436920, 2015). "It has been shown that IL-13 induces lung fibrosis by selectively stimulating TGF-β." (PMID 25775215, 2015). "Indeed, IL-4 and IL-13 have been described in lungs from patients with Idiopathic Pulmonary Fibrosis and contribute to the development of fibrosis in a number of mouse models." (PMID 22363610, 2012). "Both IL-4 and IL-13 have redundant signaling pathways with implications in pulmonary fibrosis." (PMID 23283176, 2011). "The Th2 cytokine IL-13 may be involved in inflammation and remodeling, which accompanies lung fibrosis, while the antifibrotic effects of IL-9 may be associated with a limitation of the type 2 polarization observed in pulmonary fibrosis." (PMID 21943057, 2011). "Accordingly, the development of neutralizing antibodies to IL13-PE was a concern given that these neutralizing antibodies might interfere with IL13-PE therapy in pulmonary fibrosis." (PMID 20090941, 2010). "Moreover, the role of T cells during lung fibrosis is controversial and further studies with potential advances in technology to help delineate the cellular source of IL13 would add to our current understanding." (PMID 20300636, 2010). "However, despite the presence of the neutralizing antibodies in sensitized mice, intranasal IL13-PE therapy worked effectively as a therapeutic in the bleomycin-induced pulmonary fibrosis model." (PMID 20090941, 2010). "Therefore, even though Th2 cytokine IL-13 has been involved in bleomycin-induced pulmonary fibrosis, IL-13-induced injury model seems to follow different pathways, including different participation of MMP-12." (PMID 16504062, 2006). "Another previous study reported that IL-13 may interact with TGF-β1 to induce pulmonary fibrosis." (PMID 40422811, 2025). "Therefore, we next sought to determine whether IL-5, IL-13, and AREG produced by ILC2s were altered in Hps1−/−-associated lung fibrosis." (PMID 39405112, 2024). "Additionally, the PDGF, CTGF, and IL-13 concentrations in lung tissue homogenates were significantly higher in WT mice with lung fibrosis than in saline-treated control WT mice and TG mice with lung fibrosis." (PMID 39329706, 2024). "However, recent evidence in murine models of lung fibrosis suggests that IL-10 may be profibrotic, exacerbating Th2 responses, producing IL-4 and IL-13, the recruitment of fibrocytes, and M2 macrophage polarization." (PMID 36831337, 2023). "However, there is an apparent context-dependent role for IL-13 in promoting pulmonary fibrosis." (PMID 34127548, 2021). "Therefore, we hypothesize that IL-13 induces lung fibrosis by activation of YY1 through an AKT pathway." (PMID 25775215, 2015). "Thus, he concluded that both Il-13 and Il-17A are important mediators of pulmonary fibrosis." (PMID 24484528, 2014). "In addition to the redundancy of IL-4 and IL-13 signaling through IL-4Rα/Stat6, IL-13 may signal through a distinct pathway via the IL-13Rα2 driving TGFβ1 dependent pulmonary fibrosis." (PMID 23283176, 2011). "The manner in which IL13-PE continues to work in the lung despite the presence of these neutralizing antibodies is not presently clear but we have observed that the numbers of IL-13Rα2-positive cells during pulmonary fibrosis are markedly increased (and unpublished findings)." (PMID 20090941, 2010).